SLC37A2 (solute carrier family 37 member 2)
Description:
Inorganic phosphate and glucose-6-phosphate antiporter. May transport cytoplasmic glucose-6-phosphate into the lumen of the endoplasmic reticulum and translocate inorganic phosphate into the opposite direction. Independent of a lumenal glucose-6-phosphatase. May not play a role in homeostatic regulation of blood glucose levels.
Synonyms: FLJ00171; SPX2; pp11662
Tractability: Antibody: UniProt predicts a signal peptide or a membrane-spanning region. PROTAC: ubiquitination databases record sites on it; its protein half-life has been measured.
Gene: Protein-coding gene on chromosome 11 (125,063,302 to 125,090,516, forward strand). Ensembl gene ENSG00000134955.
Subcellular location: Endoplasmic reticulum membrane
Pathways (Reactome):
Metabolism: Gluconeogenesis
Gene Ontology:
Molecular function: glucose 6-phosphate:phosphate antiporter activity; transmembrane transporter activity
Biological process: glucose-6-phosphate transport; phosphate ion transmembrane transport; transmembrane transport
Cellular component: endoplasmic reticulum membrane; extracellular exosome; membrane
Genetic constraint (gnomAD): Loss-of-function variants: 59 observed, 72.59 expected, observed/expected ratio (o/e) 0.81, 90% interval 0.66 to 1.01. The upper end of that interval is the gene's LOEUF score, 1.01, which puts it in group 4 of 6, group 1 being the genes least tolerant of losing a copy. Missense variants: 580 observed, 655.83 expected, observed/expected ratio (o/e) 0.88, 90% interval 0.82 to 0.95. Synonymous variants: 257 observed, 262.76 expected, observed/expected ratio (o/e) 0.98, 90% interval 0.88 to 1.09.
Homologues: Orthologues: chimpanzee SLC37A2 (99% identical), macaque SLC37A2 (96% identical), mouse Slc37a2 (88% identical), dog SLC37A2 (86% identical), guinea pig SLC37A2 (83% identical), pig SLC37A2 (82% identical), zebrafish slc37a2 (69% identical), tropical clawed frog slc37a2 (67% identical), Drosophila melanogaster MFS16 (52% identical), Drosophila melanogaster Picot (18% identical), Drosophila melanogaster dmGlut (18% identical), Caenorhabditis elegans vglu-2 (17% identical), and 27 more. Paralogues in human: SLC37A1 (60% identical), SLC37A3 (34% identical), SLC17A8 (18% identical), SLC17A4 (17% identical), SLC17A5 (17% identical), SLC17A6 (17% identical), SLC17A2 (17% identical), SLC17A7 (17% identical), SLC37A4 (16% identical), SLC17A1 (16% identical), SLC17A3 (15% identical), SLC17A9 (15% identical).
Diseases named in the same sentence as SLC37A2 in open-access papers:
SLC37A2 is named in the same sentence as 21 diseases in open-access papers, as found by Europe PMC text mining. Sharing a sentence is not in itself a finding about the gene and the disease. The quoted sentences say what the papers report.
Obesity (4 papers, 2018 to 2022). Accumulation of substantial excess body fat. "As SLC37A2 negatively regulates macrophage glycolysis and inflammation, we speculate that increased SLC37A2 expression in obesity might serve as a compensatory mechanism to lower intracellular glucose and attenuate obesity-induced inflammation." (PMID 32428862, 2020). "In addition to atherosclerosis assessment, we also tested whether hematopoietic cell-specific SLC37A2 deletion influences adipose tissue inflammation and/or obesity and insulin resistance under pro-atherogenic conditions." (PMID 34957260, 2021).
atherosclerosis (2 papers, 2021 to 2025). A disease characterized by the build-up of fatty material and calcium deposition in the arterial wall resulting in partial or complete occlusion of the arterial lumen. "Loss of hematopoietic cell-specific SLC37A2 impairs anti-inflammatory activities at the cell (peritoneal macrophages), tissue (liver), and systemic (plasma) levels and accelerates atherosclerosis." (PMID 34957260, 2021). "Together, our results indicate that hematopoietic SLC37A2 deletion worsens atherosclerosis, inversely associated with plasma IL-10 levels." (PMID 34957260, 2021). "Because of this, we cannot distinguish the specific contribution of macrophage SLC37A2 from other immune cells to atherosclerosis." (PMID 34957260, 2021). "In vivo disruption of hematopoietic SLC37A2 accelerates atherosclerosis under hyperlipidemic pro-atherogenic conditions." (PMID 34957260, 2021). "In diseases such as IBD and atherosclerosis, writers can modulate the expression of solute carrier family 37 member 2 (SLC37A2), macrophage scavenger receptor 1 (MSR1), and scavenger receptor class B type 1 (SR-B1), inhibiting glycolysis and lipid uptake while promoting cholesterol efflux." (PMID 40066451, 2025). "Our study suggests that hematopoietic SLC37A2 expression protects against atherosclerosis in mice." (PMID 34957260, 2021). "Whether macrophage SLC37A2 impacts in vivo macrophage inflammation and atherosclerosis under hyperlipidemic conditions is unknown." (PMID 34957260, 2021). "Since LPS, oxLDL, and IL-4 induce macrophage SLC37A2 protein expression, we speculate that induction of macrophage SLC37A2 expression promotes inflammation resolution and slows atherosclerosis progression." (PMID 34957260, 2021). "Aortic root intimal area was inversely correlated with plasma IL-10 levels, but not total cholesterol concentrations, suggesting inflammation but not plasma cholesterol was responsible for increased atherosclerosis in bone marrow SLC37A2-deficient mice." (PMID 34957260, 2021). "Since Kupffer cell replacement in Slc37a2−/− BMT mice is incomplete, the modest elevation of plasma and liver lipids in the SLC37A2Δhema mice may underestimate the harmful effect of SLC37A2 deletion on liver lipid homeostasis in the context of atherosclerosis." (PMID 34957260, 2021). "In this study, we wanted to know whether mice lacking SLC37A2 in macrophages were at an increased risk of developing atherosclerosis." (PMID 34957260, 2021). "Because SLC37A2 expression is necessary for anti-inflammatory macrophage activation in vitro and in vivo, we speculate that the impaired anti-inflammatory responses are a major driving force of enhanced atherosclerosis in the SLC37A2Δhema mice." (PMID 34957260, 2021).
breast carcinoma (2 papers, 2017 to 2021). "Moreover, TET3 knocked-down cells under normoxia exhibited an identical alternative splicing pattern of ESRP1 targets (hMENA, SLK, SCRIB, RALGPS2, SLC37A2, FNIP1, CD44, and ARHGEF1) as the hypoxic breast cancer cells." (PMID 34362878, 2021).
Caffey disease (1 paper, 2016). Caffey disease is an osteosclerotic dysplasia characterized by acute inflammation with massive subperiosteal new bone formation usually involving the diaphyses of the long bones, as well as the ribs, mandible, scapulae, and clavicles. "We identified a novel candidate gene, SLC37A2, for the corresponding human disease, infantile cortical hyperostosis, also known as Caffey disease, and implicated SCARF2 and FAM20C variants in the canine forms of van den Ende-Gupta and Raine syndromes, respectively." (PMID 27187611, 2016). "Canine CMO is equivalent to Caffey disease and our data reveals a novel candidate gene, SLC37A2, for the syndrome." (PMID 27187611, 2016). "CMO is a clinical equivalent to an infantile cortical hyperostosis (Caffey disease) for which SLC37A2 is a new candidate gene." (PMID 27187611, 2016).
colitis (1 paper, 2026). Inflammation of the colon. "In addition, human umbilical cord-derived mesenchymal stem cell exosomes (hucMSC-Ex) have been shown to alleviate colitis in mice by enhancing M2 macrophage polarization via the METTL3–solute carrier family 37 member 2 (Slc37a2)–YTHDF1 axis, thereby suppressing pro-inflammatory macrophage activity." (PMID 41376856, 2026).
congenital hyperinsulinism (1 paper, 2018). "SLC37A1 seems to be required for lipid biosynthesis in cancer cell lines, SLC37A2 has been proposed as a vitamin D and a phospho-progesterone receptor target gene, while mutations in the SLC37A3 gene appear to be associated with congenital hyperinsulinism of infancy." (PMID 29719821, 2018).
glioma (1 paper, 2023). A benign or malignant brain and spinal cord tumor that arises from glial cells (astrocytes, oligodendrocytes, ependymal cells). "Higher expression in G6PC3, SLC37A2, and SLC37A4 was found in GBM tumor tissues in comparison to low-grade glioma and healthy tissue." (PMID 38034009, 2023). "Next, qPCR analysis revealed that the expression of G6PC3, SLC37A2, and SLC37A4 was considerably higher in all four glioma cell lines tested when compared to HepG2 cells." (PMID 38034009, 2023).
hepatoma (1 paper, 2023). "Consistent with our in silico data analysis, functional experiments were performed using several established GBM-derived cell lines in which high expression of G6PC3, SLC37A2, and SLC37A4 in comparison to HepG2 hepatoma cells was observed." (PMID 38034009, 2023).
hyperostosis (1 paper, 2016). Excessive thickening of bone. "SLC37A2 is a glucose-phosphate transporter in osteoclasts, and its defect suggests an impaired glucose homeostasis in developing bone, leading to hyperostosis." (PMID 27187611, 2016).
mastitis (1 paper, 2023). Inflammation of breast tissue during lactation or postpartum due to an obstructed duct or infection. "In this study, the ZRANB3, PIAS1, ACTR3, LPCAT2, MGAT5, and SLC37A2 genes in Xinjiang brown cattle, which are associated with mastitis resistance, were identified using a GWAS." (PMID 37372369, 2023). "These six genes (ZRANB3, PIAS1, ACTR3, LPCAT2, MGAT5, and SLC37A2) are all potentially associated with mastitis resistance." (PMID 37372369, 2023).
osteosarcoma (1 paper, 2023). A usually aggressive malignant bone-forming mesenchymal neoplasm, predominantly affecting adolescents and young adults. "Several amino acid transporters, such as SLC44A5, SLC9B2, and SLC37A2, were significantly decreased after NACT, which might contribute to the amino acid deprivation in osteosarcoma after NACT." (PMID 37457661, 2023).
cancer (4 papers, 2017 to 2023). A tumor composed of atypical neoplastic, often pleomorphic cells that invade other tissues. "The vital role of risk signature genes identified in this study has been previously reported in cancer except for SLC37A2." (PMID 35789548, 2023). "Although no studies have been conducted in cancer models, SLC37A2 is associated with at least 17 other public datasets that define stem cell genes or proteins." (PMID 28412963, 2017). "SLC37A2 has not been reported to be involved in cancerigenesis or cancer progression." (PMID 36386788, 2022).
SLC37A2 also shares sentences with these, for which no sentence is quoted: tumor (2 papers); brain cancer (1); breast tumor (1); glioblastoma (1); Insulin resistance (1); low grade glioma (1); lysosomal storage disorder (1); osteonecrosis (1); Raine syndromes (1).